PSMB8 (proteasome 20S subunit beta 8)
Diseases named in the same sentence as PSMB8 in open-access papers (continued):
Sharing a sentence is not in itself a finding about the gene and the disease.
glioma (17 papers, 2018 to 2025). A benign or malignant brain and spinal cord tumor that arises from glial cells (astrocytes, oligodendrocytes, ependymal cells). "Analysis of 110 glioma and 30 normal brain tissue arrays indicated that PSMB8 levels were significantly higher in tumor tissues, and elevated PSMB8 protein expression was associated with higher grades." (PMID 40335825, 2025). "High levels of PSMB8 are associated with more aggressive gliomas, and inhibition of PSMB8 was shown to reduce glioma cell proliferation and migration, as well to decrease glioblastoma tumor angiogenesis." (PMID 34944095, 2021). "Our findings demonstrate that PSMB8 depletion not only suppressed glioma cell proliferation and migration but also induced apoptosis via activation of the transforming growth factor beta (TGF-β) signaling pathway." (PMID 40335825, 2025). "In the current research, we explored the biological function of PSMB8 during the proliferation, migration and apoptosis processes of glioma cells." (PMID 40335825, 2025). "Overall, our findings highlight PSMB8's pivotal role in glioma pathophysiology and its potential as a prognostic marker." (PMID 40335825, 2025). "Collectively, our study revealed that PSMB8 can not only be a useful prognostic factor in glioma patients, but also a predictive marker of prognostic factors and novel therapeutic target by blocking key proteins of TGF-β signaling." (PMID 40335825, 2025). "To uncover the mechanism by which PSMB8 facilitates malignant glioma cell behavior, we applied RNA sequencing analysis to Co.sh, sh-M#1, and sh-M#2 LN229 cells to determine transcriptional changes." (PMID 40335825, 2025). "To further investigate PSMB8 expression in gliomas, we explored its expression level in gliomas and normal brain tissues using immunohistochemistry." (PMID 40335825, 2025). "Concurrently, in the validation set (age, 49.9 ± 11.6 years), there were 34 (82.9%) high PSMB8 expression and 7 (17.1%) low PSMB8 expression gliomas." (PMID 40335825, 2025). "Previous research in glioma demonstrated that PSMB8 promotes tumor cell proliferation and migration by downregulating cyclin family proteins, N-cadherin, and vimentin, while upregulating E-cadherin via activation of the ERK1/2 and PI3K/AKT signaling pathways." (PMID 40335825, 2025). "This study identifies the proteasome subunit beta type-8 (PSMB8/LMP7) as a promising prognostic biomarker for glioma." (PMID 40335825, 2025). "PSMB8 was found to be an important regulator in the process of glioma cell migration, proliferation and apoptosis mediated by ERK1/2 and PI3K-AKT pathways, which shares common pathways of invasion and angiogenesis with embryo implantation." (PMID 38371594, 2024). "PSMB8 has also been demonstrated to influence glioma cell migration, proliferation, and apoptosis via modifying the PI3K/AKT signaling pathway." (PMID 37974228, 2023). "Other studies have reported that PSMB8 regulation of migration and proliferation in less invasive grades of gliomas was dependent on PI3K and ERK pathways." (PMID 34944095, 2021). "Previous research has shown that PSMB8 regulates glioma cell differentiation, cell migration, proliferation, and apoptosis, which are similar processes to embryo implantation." (PMID 34571957, 2021). "The target gene of miR-451-5p, PSMB8, is known as a direct regulator of cell migration, proliferation, and the apoptosis of glioma cells through modulating ERK1/2 and PI3K/AKT signaling pathways." (PMID 34571957, 2021). "PSMB8, a protein contributes to the complete assembly of 20S proteasome complex, regulates glioma cell migration, proliferation, and apoptosis." (PMID 30356407, 2018). "However, our study focused on uncovering the role of PSMB8-mediated malignant glioma phenotypes through the activation of the TGFBR1/2-SMAD2/3 axis." (PMID 40335825, 2025).
glioma (continued). "Additionally, it was discovered that the ERK1/2 and PI3 K/AKT signaling pathways triggered by PSMB8 played a role in the migration and proliferation processes of glioma cells." (PMID 40335825, 2025). "Moreover, we investigated the downstream signaling pathway via knockdown of PSMB8 in glioma cell lines." (PMID 40335825, 2025). "Also, correlative studies predicted that PSMB8 has a carcinogenic role in lower-grade glioma, uveal melanoma and pancreatic adenocarcinoma." (PMID 40698074, 2025). "Besides, the IHC confirmed that high levels of PTPN6 and PSMB8 expression occurred in glioma tissues." (PMID 35127714, 2021). "Suppression of PSMB8 may be a promising strategy for the treatment of PSMB8-overexpressing gliomas." (PMID 37974228, 2023). "This subunit, encoded by PSMB8 gene, has a wide range of expression among different cancers, which have been evaluated in non-small cell lung carcinoma (NSCLC), renal cell carcinoma, glioma, colorectal cancer, triple-negative breast carcinoma (TNBC), laryngeal, and hypopharyngeal carcinoma." (PMID 34944095, 2021). "For example, PSMB8 expression decreased survival in gastric cancer and PSMB9 expression correlated with poor outcomes in glioma." (PMID 40698074, 2025). "After silencing PSMB8, reduced expression of TGFBR1 and TGFBR2 led to decreased phosphorylation of SMAD2/3, which inhibited the malignant behavior of glioma cells." (PMID 40335825, 2025). "Our findings indicate that Shikonin-induced programed necrosis leads to a downregulation of proteasome activity and a decrease in the expression of immune proteasome subunits PSMB8/9/10 and PSME1/2/3, contributing to the attenuation of stemness in gliomas." (PMID 39619148, 2024). "Numerous studies have demonstrated the regulatory roles of PSMB8, PSMB9, and PSMB10 in glioma proliferation, migration, angiogenesis, inflammatory response, and hypoxia-related tumor characteristics." (PMID 39619148, 2024). "We further investigated whether the elevated expression of PSMB8 has a connection with the activation of the TGF-β pathway, thereby accelerating glioma progression." (PMID 40335825, 2025). "Targeted inhibition of PSMB8 may represent a therapeutic strategy to overcome TMZ resistance and improve glioma patient outcomes." (PMID 40335825, 2025). "Moreover, radiomics was used to preoperatively predict PSMB8 expression and it highlighted that PSMB8 is a prognostic marker and treatment target for temozolomide (TMZ)-resistant glioma." (PMID 40335825, 2025). "In other words, the expression level of PSMB8 is significantly higher in high-grade gliomas as opposed to low-grade gliomas." (PMID 40335825, 2025). "PSMB8 regulation of cell growth and migration, possibly via ERK1/2 (extracellular signal-regulated protein kinase) and AKT (serine/threonine kinase 1) signaling, was also observed in glioma cells." (PMID 37261527, 2023). "This new direction of our investigation explored a different molecular mechanism compared to the previously identified pathways, which may offer potential therapeutic targets that have not been considered before in the context of glioma treatment related to PSMB8's actions." (PMID 40335825, 2025).
gastric cancer (15 papers, 2016 to 2025). A primary or metastatic malignant neoplasm involving the stomach. "A previous study found that PSMB8 overexpression correlated with the advancement of gastric cancer, particularly in characteristics linked to tumor invasion and lymph node metastases." (PMID 37974228, 2023). "In this study, we identified Psmb8 as a putative therapeutic target based on gene expression profiling from our accelerated Helicobacter-induced gastric cancer mouse model." (PMID 41228214, 2025). "Our accelerated Helicobacter-induced gastric cancer mouse model allowed us to identify several differentially expressed genes (DEGs), including Psmb8 (proteasome subunit beta type 8, also called Lmp7), which was also found to be elevated in GC patient samples." (PMID 41228214, 2025). "In contrast, PSMB8 was downregulated in gastric cancer tissue and was found to inhibit proliferation and promote apoptosis in cancer cells." (PMID 37974228, 2023). "Similar to PSMB5, Proteasome 20S subunit beta 8 (PSMB8) overexpression correlates with the progression of gastric cancer, its inhibition in glioblastoma increases apoptosis and decreases angiogenesis, and its mutation leads to inflammation and lipodystrophy." (PMID 37111759, 2023). "It was reported that PSMB8 overexpression was related to gastric cancer development and progression, especially aspects correlated with the depth of tumor invasion and lymph node metastasis." (PMID 35933405, 2022). "The overexpression of PSMB8 contributes to the progression of gastric cancer, which is related to the degree of gastric cancer differentiation, the depth of tumor invasion, lymph node metastasis and depth of invasion." (PMID 35127714, 2021). "We next performed an immunohistochemistry analysis of 385 gastric cancer patients to evaluate the relationship between expression of PSMB8 or PBK and clinicopathological characteristics." (PMID 26894977, 2016). "Although it has been reported that carcinoma cell motility and invasiveness occur via the PI3K and MAP kinase pathways, we observed unaltered activation of Akt, ERK, or p38 following PSMB8 or PBK downregulation in gastric cancer." (PMID 26894977, 2016). "Consistent with this, proteasome subunit PSMA6 and PSMB8 were more highly expressed in gastric cancer patients with a poor prognosis compared with patients with a good prognosis." (PMID 26894977, 2016). "Consistent with our microarray results, a Kaplan-Meier survival analysis revealed that gastric cancer patients displaying high protein expression of either PSMB8 or PBK had a decreased survival rate." (PMID 26894977, 2016). "Nevertheless, what this study suggests is that gastric cancer patients with high expression levels of PSMB8 in their tumors may benefit from targeted treatment with carfilzomib." (PMID 41228214, 2025). "Together, ERBB2, VIM, and PSMB8 may be effective targets in gastric cancer, but more experimental investigations and clinical trials are needed." (PMID 31949544, 2019). "Finally, the expression of four hub genes (ERBB2, VIM, EGR1, and PSMB8) was found to be related to the prognosis of HER2-positive (HER2+) gastric cancer." (PMID 31949544, 2019). "However, knockdown of each gene significantly decreased gastric cancer cell migration and invasion, suggesting that PSMB8 and PBK are involved in gastric cancer progression." (PMID 26894977, 2016). "Furthermore, immunohistochemistry analysis of 385 gastric cancer patients revealed that increased nuclear expression of PSMB8 and PBK was correlated with depth of invasion, lymph node metastasis, and lower survival rates." (PMID 26894977, 2016). "The expression of PSMB8 (proteasome subunit beta type 8), a component of the 20S proteolytic core particle, is generally increased in tumor cell lines and correlated with poor prognosis; its reduction inhibits the progression and invasion of gastric cancer and glioblastoma." (PMID 35486664, 2022).
gastric cancer (continued). "The expression of PSMB8, IFIT2, and IFIT1 had prognostic value in gastric cancer at different stages." (PMID 31949544, 2019). "The roles of proteasome subunit beta type-8 (PSMB8) and EGR1 in trastuzumab-resistant gastric cancer are controversial." (PMID 31949544, 2019). "Therefore, the roles of PSMB8 and EGR1 in trastuzumab-resistant gastric cancer need to be further investigated." (PMID 31949544, 2019). "We propose that PSMB8 and PBK could be useful biomarkers for identifying gastric cancer patients with a poor prognosis." (PMID 26894977, 2016). "Knockdown of PSMB8 and PBK decreased gastric cancer cell migration and invasion, respectively." (PMID 26894977, 2016). "Although we clearly suggested that PSMB8 and PBK promote the migration and invasion of gastric cancer cells, PSMB8 and PBK are not sufficient to proliferation by themselves in gastric cancer cells." (PMID 26894977, 2016). "We next performed immunohistochemistry staining to detect PSMB8 and PBK protein expression in 385 gastric cancer specimens that were not the same as those used in the microarray studies." (PMID 26894977, 2016). "The molecular mechanism by which PSMB8 and PBK promote gastric cancer cell progression has not been elucidated." (PMID 26894977, 2016). "We focused on PSMB8 and PBK, whose functions in gastric cancer have not been reported." (PMID 26894977, 2016).
colitis (14 papers, 2011 to 2024). Inflammation of the colon. "Knockout of PSMB8 in mice was shown to prevent colitis-associated carcinogenesis." (PMID 34944095, 2021). "In a similar vein, several studies also reported that PSMB8 inhibitors reversed autoreactive immune responses and showed therapeutic effects in animal models of autoimmune encephalomyelitis, colitis, and Hashimoto’s thyroiditis." (PMID 35213968, 2022). "For instance, the pro-tumorigenic role of PSMB8 in colorectal cancer is related to its role in colitis-induced chronic inflammation, which can drive neoplastic transformation of intestinal epithelium in the colon." (PMID 34944095, 2021). "In line with this, LMP7 (=PSMB8) knockout mice are protected from DSS colitis." (PMID 37818353, 2023).
viral infection (14 papers, 2011 to 2025). "Our data show that PSMB8, 9 and 10 are found in both cell lysates and purified proteasomes upon virus infection, therefore indicating that they are incorporated into the complex." (PMID 40872920, 2025). "In addition, PSMB8 is involved in regulating cytokine secretion during viral infection." (PMID 37007947, 2023). "Unlike for Atlantic salmon, for which none of the biomarkers showed particular discrimination between viral disease and BKD, in Chinook salmon, five biomarkers—UBL1 (PSMP2), LGAL3BP (GAL3), IFI44 (both A and C paralogs) and PSMB8—were discriminatory." (PMID 28702195, 2017). "Of note, immunoproteasome subunit beta types PSMB8, PSMB9, and PSMB10, together with the PSME2 subunit of the immunoproteasome specific regulatory 11S cap structure, strongly indicated increased levels of immunoproteasomes with progressing virus infection." (PMID 37112941, 2023). "While we found that stimulation with exogenous IFNs could induce PSMB8, PSMB9 and PSMB10 expression in both cell lines, neither could produce the cytokines upon virus infection." (PMID 40872920, 2025).
autoimmune disease (13 papers, 2014 to 2025). A disorder resulting from loss of function or tissue destruction of an organ or multiple organs, arising from humoral or cellular immune responses of the individual to their own tissue constituents. "PSMB8 is implicated in perturbation of the immune system in autoimmune disease and our findings indicate that its role in immune modulation within the context of breast cancer metastasis is worthy of further, focused investigation." (PMID 28051153, 2017). "Genes within MHC class II loci along with genes involved in antigen processing and presentation i.e., proteasome subunit beta 8 (PSMB8) and transporter associated with antigen processing 1 (TAP1) have been reported to be associated with several autoimmune diseases including vitiligo." (PMID 28700671, 2017). "Major histocompatibility complex (MHC) class-II linked genes proteasome subunit beta 8 (PSMB8) and transporter associated with antigen processing 1 (TAP1), involved in antigen processing and presentation have been reported to be associated with several autoimmune diseases including vitiligo." (PMID 28700671, 2017). "Immunoproteasome inhibitors have been shown to ameliorate symptoms in preclinical models of different autoimmune diseases, and KZR-616, a drug targeting both PSMB8 and PSMB9, has been tested in a Phase II trial of systemic lupus erythematosus." (PMID 37581620, 2023). "Resveratrol may potentially be used for downregulation of chronic inflammation during autoimmune diseases, to inhibit the acquired immunity genes induced by LPS and other plant and viral toxins by downregulating gene expression of LMP7 (PSMB8), IFN-γ." (PMID 36361735, 2022).
lipodystrophy (13 papers, 2014 to 2025). A congenital or acquired disorder characterized by abnormal loss or redistribution of the adipose tissue in the body. "The missense mutation in PSMB8 disturbs the functions of immunoproteasomes, which in turn causes lipodystrophy." (PMID 27225296, 2016). "In any case, distinguishing between PSMB8 mutations and other altered genes that contribute to lipodystrophy might shed light on the pathophysiology of lipodystrophy." (PMID 27225296, 2016). "Autoinflammation, lipodystrophy, and dermatosis syndrome (ALDD) can be caused by homozygous mutations in the PSMB8 gene (OMIM: # 256040), P SKAT.corr = 0.0246 and Pburden.test.corr = 0.00179, ORburden.test = 0.64 and CI 95%.burden.test = (0.48, 0.84)." (PMID 30863397, 2019). "A missense mutation in PSMB8, G197E, results in the reduced expression of PSMB8, elevated IL-6 production, and lipodystrophy through disturbed adipocyte differentiation, high-level neutrophilia in the dermis, and accumulation of ubiquitinated proteins in PSMB8 mutated cells." (PMID 40552831, 2025). "Indeed, one participant had a CNV spanning three recessive immune genes PSMB8, TAP1, and TAP2, which are associated with autoinflammation, lipodystrophy, dermatosis syndrome (PSMB8), and type I bare lymphocyte syndrome (TAP1 and TAP2)." (PMID 24672537, 2014).
glioblastoma (12 papers, 2021 to 2025). The most malignant astrocytic tumor (WHO grade IV). "But overexpressed PSMB8 was reported to infer poor prognosis in acute myeloid leukemia and glioblastoma." (PMID 40334200, 2025). "As such, ONX-0914, the most studied ImP inhibitor, blocks PSMB8 and has been reported to induce cell death in pre-clinical models of glioblastoma, acute lymphoblastic leukemia, NSCLC, colorectal, gastric and castration-resistant prostate cancers." (PMID 40698074, 2025). "In glioblastoma, PSMB8 inhibition induces apoptosis and inhibits migration and invasion through PI3K/AKT cascades." (PMID 36428804, 2022). "In glioblastoma, PSMB8 inhibition enhanced apoptosis and suppressed migration and invasion through PI3K/AKT regulation." (PMID 35933405, 2022). "In conclusion, the PSMB8 inhibitor ONX-0914 reduced glioblastoma progression by inducing cell cycle arrest, apoptosis, and autophagy." (PMID 36428804, 2022). "PSMB8 inhibition also decreases tumor angiogenesis in glioblastomas by reducing vascular endothelial cell growth factor (VEGFA) levels." (PMID 36428804, 2022). "Previous studies have shown that inhibiting PSMB8 expression in glioblastoma reduces tumor progression." (PMID 36428804, 2022). "In glioblastomas, Psmb8 (LMP7) inhibition decreased tumor angiogenesis and was designated as an independent unfavorable prognostic marker." (PMID 35395831, 2022). "Previous studies have shown that inhibiting PSMB8 expression in a glioblastoma reduces tumor progression and angiogenesis." (PMID 36428804, 2022). "Elevated expression of PSMB8 was found in resected glioblastomas, and inhibition of PSMB8 reduced the migration and invasion of tumor cells in vitro." (PMID 34944095, 2021). "Moreover, another study indicated that in glioblastoma, high expression of PSMB8 could increase tumor angiogenesis by enhancing the expression of vascular endothelial growth factor (VEGF)-A, vascular endothelial growth factor receptor (VEGFR), and CD31." (PMID 40335825, 2025). "For example, treatment of glioblastoma cell line with ONX‐0914, a selective immunoproteasome inhibitor targeting PSMB8, has shown the potential to reduce tumour progression by inducing cell cycle arrest and autophagy." (PMID 37097039, 2023). "In this study, we clarified that the PSMB8 inhibitor, ONX-0914, arrested cell cycle, and induced apoptosis and autophagy in three human glioblastoma cells." (PMID 36428804, 2022). "In the orthotopic mouse model, inducible knock-down of PSMB8 dampened the expression of vascular endothelial growth factor (VEGF) and CD31; and thus, favored invasive capacity in glioblastoma." (PMID 34650125, 2021).